COL4A1 (collagen type IV alpha 1 chain)
Diseases named in the same sentence as COL4A1 in open-access papers (continued):
Sharing a sentence is not in itself a finding about the gene and the disease.
myopathy (15 papers, 2011 to 2026). A disease of the muscle in which the muscle fibers do not function properly. "The morphology of the oviduct muscle will be changed in COL4A1 mutants, which then causes severe myopathy with centronuclear myofibers." (PMID 29890619, 2018). "Mice harboring a semi-dominant Col4a1 mutation have ocular dysgenesis, cerebral cortical lamination defects and myopathy." (PMID 21625620, 2011). "Determination of the primary site of pathogenesis for myopathy will likely require conditional expression of the Col4a1 mutation." (PMID 21625620, 2011). "Understanding the precise mechanism underlying myopathy is complicated by the presence of COL4A1 in basement membranes of the sarcolemma, myotendonous junctions and neuromuscular junctions." (PMID 21625620, 2011). "In addition, the same Authors pointed out the importance of the endothelial cell damage and the apoptosis promoted by UPR in the occurrence of the growth-related muscular abnormalities in broilers, in accordance with the potential pathogenic mechanisms of COL4A1-related myopathies." (PMID 33469097, 2021). "We define parameters for reducing stroke and myopathy in Col4a1 mutant mice by pharmacologically promoting heterotrimer secretion." (PMID 29895609, 2018). "We identified therapeutic windows for alleviating ICH and myopathy and demonstrate a dose dependency for disease outcomes in response to postnatal 4PBA treatment in Col4a1 mutant mice." (PMID 29895609, 2018). "Using a combination of histological, molecular, and biochemical approaches, we show that heterozygous Col4a1 mutant mice have ocular dysgenesis, neuronal localization defects, and myopathy characteristic of MEB/WWS." (PMID 21625620, 2011). "More in detail, it was demonstrated the contribution of vascular defects to the development of COL4A1-related myopathies, probably due to failure of the type IV collagen secretion from endothelial cells and its intracellular accumulation, resulting in the ER stress condition." (PMID 33469097, 2021). "Future research works could be carried out to investigate the possible effects of COL4A1 mutations in chickens and more generally the role of ECM disorders in the etiology and pathogenesis of WS and WB myopathies." (PMID 33469097, 2021). "To test the relative impact of early versus late intervention, we evaluated ICH and myopathy severity in Col4a1+/Δex41 mice for which 4PBA was either discontinued or initiated at weaning [treated from E9.5 to postnatal day (P) 25 or from P25 to 3MO, respectively]." (PMID 29895609, 2018). "The pathogenesis of COL4A1-related ICH and myopathy is thought to result from impaired heterotrimer secretion into basement membranes, and we previously demonstrated the therapeutic potential of promoting secretion using 4PBA administration in Col4a1+/Δex41 mice." (PMID 29895609, 2018). "Notably, ICH and myopathy in approximately half of the Col4a1+/Δex41 mice from the cohort provided with 25 mM 4PBA from birth were milder than the mildest case of the untreated Col4a1+/Δex41 cohort; however, the population showed broad ranges of severities." (PMID 29895609, 2018). "Thus, myopathy resulting from mutations in basement membrane components LAMA2 and COL4A1 might share a common pathogenic mechanism whereby contraction-induced load leads to muscle fiber detachment." (PMID 21625620, 2011). "Here, we used different 4PBA treatment paradigms in Col4a1 mutant mice to define the therapeutic parameters of promoting heterotrimer secretion for treatment of COL4A1-related ICH and myopathy." (PMID 29895609, 2018). "Using different treatment paradigms, we show that the maximal therapeutic benefits of 4PBA for suppressing Col4a1-related ICH and myopathy are achieved when treatment is initiated prenatally." (PMID 29895609, 2018).
myopathy (continued). "To this end, we provided Col4a1+/Δex41 mice with 25 mM, 50 mM or 100 mM 4PBA from birth (P0) or weaning (P25) until assessment of ICH and myopathy at 3MO, 24 h after grip strength measurement and exercise challenge." (PMID 29895609, 2018). "We show that genetic context is an important factor contributing to the variable penetrance and severity of Col4a1-related diseases and that the CAST/EiJ strain can modify myopathy." (PMID 21625620, 2011). "Although our findings clearly demonstrate the therapeutic potential of pharmacologically promoting heterotrimer secretion to reduce COL4A1-related ICH and myopathy, they also highlight important limitations when considering the translational potential of this approach." (PMID 29895609, 2018). "When transient 4PBA treatment was provided postnatally from P0 to P25, the severities of ICH and myopathy were not significantly different between treated and untreated Col4a1+/Δex41 mice." (PMID 29895609, 2018). "Because Col4a1+/ex40 mice display ocular and cerebral abnormalities characteristic of MEB/WWS, we hypothesized that they would also have myopathy." (PMID 21625620, 2011). "We show that, depending on the genetic context; Col4a1+/Δex40 mice recapitulate the pathophysiological hallmarks of MEB/WWS, including ocular anterior segment dysgenesis, optic nerve hypoplasia, cortical lamination defects and myopathy." (PMID 21625620, 2011). "Compared to Col4a1+/+ littermates, Col4a1+/Δex40 mice had occasional split muscle fibers and a significant increase in the number of non-peripheral nuclei – a measure of myopathy." (PMID 21625620, 2011). "Moreover, there were significantly fewer muscle fibers with non-peripheral nuclei in CASTB6F1 Col4a1+/Δex40 mice compared to C57BL/6J Col4a1+/Δex40 mice (p<0.05), indicating that the CAST/EiJ strain has one or more loci that can also ameliorate Col4a1-induced myopathy." (PMID 21625620, 2011). "Importantly, myopathy was genetic background-dependent, which implies that in resistant genetic contexts Col4a1- induced myopathy might not be detected but that on permissive genetic backgrounds, myopathy could be severe." (PMID 21625620, 2011).
cardiovascular disease (6 papers, 2013 to 2024). "In addition, HGPS VSMCs exhibit elevated levels of COL4A1 at late passage than early passage, consistent with higher passage VSMCs exhibiting signatures of cardiovascular disease." (PMID 38576084, 2024).
vasculopathy (6 papers, 2022 to 2025). "Therefore, the sustainably high concentrations of COL4A1 in our patients may indicate the persistence of the SSc-associated vasculopathy after AHSCT, despite improvement of fibrosis, as previously reported." (PMID 35488348, 2022). "Concurrently, an exhaustive review of previously documented patients with COL4A1/2-related vasculopathy was conducted by sourcing data from PubMed, Web of Science, Google Scholar, and Ichushi databases." (PMID 38392956, 2024). "The downregulation of PLAU aligns with impaired fibrinolysis observed in GD1-associated bone crises, while COL4A1 overexpression may reflect aberrant angiogenesis, a feature increasingly recognized in GD1 vasculopathy." (PMID 41323100, 2025). "In the current study, preliminary evidence suggests that decreased methylation of COL4A1 and COL4A2 may play a role in disrupting blood vessel architecture and contribute to vasculopathy in individuals with Fabry disease." (PMID 41150803, 2025).
infection (5 papers, 2013 to 2025). The state of being infected such as from the introduction of a foreign agent such as serum, vaccine, antigenic substance or organism. "HBZ was previously shown to enhance HTLV-1 infection by activating the expression of ICAM1 and MYOF, and in this study, we found that HBZ upregulates two additional cellular genes involved in infection: COL4A1 and GEM." (PMID 37375521, 2023). "Importantly, H. pylori infection of AGS cells induced strong upregulation of COL4A1 and CTNNB1 and significantly increased proliferation, clonogenicity, and migration, demonstrating a direct infection-driven oncogenic response." (PMID 41291892, 2025). "For validation of outlined interactions and to legitimate calculated miR-29a-target interactions and to prove biological significance, we examined the expression of miR-29a, AKT3, BAIAP2, COL4A1, VCL, CAV2 and CDC42 over the course of infection by means of RT-qPCRs." (PMID 23826261, 2013).
adenocarcinoma (4 papers, 2020 to 2024). A common cancer characterized by the presence of malignant glandular cells.
neurodegenerative disease (3 papers, 2022). A disorder of the central nervous system characterized by gradual and progressive loss of neural tissue and neurologic function. "Overall, our findings encourage further investigation on the role of col4a1 and col25a1 in the biology of the vertebrate brain as well as the onset of aging and neurodegenerative diseases." (PMID 35163698, 2022). "Our work may stimulate further investigation on the role of col4a1 and col25a1 in the onset of neurodegenerative diseases, and more in general in the aging process." (PMID 35163698, 2022).
retinopathy (3 papers, 2016 to 2021). "In the retina, Col4a1 and Col4a2 are mainly present in basement membranes of the choriocapillaries vasculature and Col4a1 mutation causes highly penetrant and progressive retinopathy that is secondary to vascular defects." (PMID 33918807, 2021). "The data demonstrate that the Col4a1 mutation causes highly penetrant and progressive retinopathy that is secondary to vascular defects." (PMID 26813606, 2016). "To identify the cell-type responsible for pathogenesis we generated a conditional Col4a1 mutation and determined that primary vascular defects underlie Col4a1-associated retinopathy." (PMID 26813606, 2016). "In order to better understand the consequences of COL4A1 mutations in patients we characterized retinopathy in Col4a1 mutant mice." (PMID 26813606, 2016). "We propose that patients with COL4A1 or COL4A2 mutations may be at risk for developing vision-threatening retinopathy." (PMID 26813606, 2016). "Finally, we developed a conditional Col4a1 mutation with which to genetically dissect differential cell-type contributions and identify the primary site of pathogenesis for retinopathy." (PMID 26813606, 2016). "Histopathological analysis of the retina did show a trend towards reduced optic nerve `cupping’, which in Col4a1 mutant mice reflect optic nerve hypoplasia, but signs of retinopathy were also observed." (PMID 30351356, 2019).
heart diseases (1 paper, 2021). "Several reports have shown that mutations in Col4a2 and Col4a1 are linked to heart diseases." (PMID 34648499, 2021).
inflammation (1 paper, 2017). Aberrant reaction of the microcirculation characterized by movement of fluid and leukocytes from the blood into extravascular tissues. "Our data do not distinguish between a secondary consequence of ocular inflammation or abnormal signaling and/or interaction between the lens and the periocular mesenchyme in the pathogenesis of Col4a1-related ASD; importantly these potential mechanisms are not mutually exclusive." (PMID 28237965, 2017).
neurogenetic diseases (1 paper, 2020). "This study presents the neurologic phenotypes of 2 brothers with a novel homozygous COL4A1 mutation that was identified in a large Turkish consanguineous cohort of neurogenetic diseases." (PMID 32042920, 2020).
COL4A1 also shares sentences with these, for which no sentence is quoted: polymicrogyria (5 papers); genetic disorders (4); head and neck squamous cell carcinoma (4); muscle cramp (4); neurological disease (4); CADASIL (3); cardiac arrhythmia (3); colorectal cancer (3); Fabry disease (3); hereditary diffuse leukoencephalopathy with spheroids (3); oral carcinoma (3); Rieger anomaly (3); thyroid papillary carcinoma (3); X-linked adrenoleukodystrophy (3); Ataxia (2); Cerebral Autosomal Dominant Arteriopathy with Subcortical Infarcts and Leukoencephalopathy (2); chronic apical periodontitis (2); colitis (2); collagenopathies (2); connective tissue disorder (2); fibrosing alveolitis (2); hereditary hemorrhagic telangiectasia (2); leukodystrophies (2); migraine with aura (2); muscle disorders (2); oral squamous cell carcinoma (2); pancreatic adenocarcinoma (2); Porencephalic cyst (2); Retinal hemorrhage (2); retinal vasculopathy with cerebral leukodystrophies (2).
A further 132 diseases each share a sentence with COL4A1 in 2 papers or fewer.